JAZF1 (JAZF zinc finger 1)
Diseases named in the same sentence as JAZF1 in open-access papers (continued):
Sharing a sentence is not in itself a finding about the gene and the disease.
metabolic disorders (3 papers, 2021 to 2025). "In turn, this can also lead to novel therapeutic approaches targeting JAZF1 association with NuA4/TIP60 to treat specific metabolic disorders." (PMID 37091973, 2023). "Several reports show that genetic variants within JAZF1 cause metabolic disorders that downregulate JAZF1 expression, and these genetic variations are also correlated with decreased body mass index (BMI) and waist circumference." (PMID 34407873, 2021). "Here, variants from six genes, namely, JAZF1, TSPAN8, THADA, ADAMTS9, CDC123/CAMK1D, and NOTCH2, are genes closely associated with T2DM and metabolic disorders." (PMID 34407873, 2021). "We used the 3T3-L1 preadipocyte—a widely used model for adipogenic differentiation and mouse embryonic fibroblasts (MEFs) from the homozygous JAZF1 deletion (JAZF1-KO) mice—to explore the JAZF1 function in adipocyte differentiation related to metabolic disorders." (PMID 34407873, 2021).
infection (1 paper, 2018). The state of being infected such as from the introduction of a foreign agent such as serum, vaccine, antigenic substance or organism. "Similarly, we established DU145 cell lines with Jazf1 knock-down using shRNA infection." (PMID 29416651, 2018).
JAZF1 also shares sentences with these, for which no sentence is quoted: psoriasis (4 papers); cardiac disease (3); gastric cancer (2); Papillary Thyroid Carcinoma (2); adult onset asthma (1); allergic disease (1); allergic rhinitis (1); autosomal recessive osteopetrosis (1); benign prostatic hyperplasia (1); carcinosarcoma (1); colorectal cancer (1); COVID-19 (1); Crohn disease (1); dilated cardiomyopathy (1); dyslipidaemia (1); endometrial neoplasm (1); gestational diabetes (1); immunoglobulin A deficiency (1); Impaired glucose tolerance (1); liver fibrosis (1); melanoma (1); Miscarriage (1); myopia (1); neurological disorders (1); nodular goiter (1); nonalcoholic fatty liver disease (1); Onset (1); prostate adenocarcinoma (1); schizophrenia (1); synovial sarcoma (1).
A further 2 diseases each share a sentence with JAZF1 in 1 paper.